LINC00911 (long independently transcribed non-coding RNA 911)
Gene: Long non-coding RNA gene on chromosome 14 (85,393,828 to 85,420,550, forward strand). Ensembl gene ENSG00000259107.
Diseases named in the same sentence as LINC00911 in open-access papers:
LINC00911 is named in the same sentence as 2 diseases in open-access papers, as found by Europe PMC text mining. Sharing a sentence is not in itself a finding about the gene and the disease. The quoted sentences say what the papers report.
breast carcinoma (1 paper, 2020). "High expression of LINC00911, H19, and MIRLRT7BHG, respectively, predicted poor survival in TN breast cancer." (PMID 32190687, 2020).
tumor (1 paper, 2021). "Notably, LINC00911 and RFX3-AS1 are known as oncogenes, whereas STXBP5-AS1 is known as a tumor suppressor." (PMID 33477683, 2021).